CXCR4 (C-X-C motif chemokine receptor 4)
Diseases named in the same sentence as CXCR4 in open-access papers (continued):
Sharing a sentence is not in itself a finding about the gene and the disease.
breast carcinoma (continued). "In 81.8% of primary HER2-positive breast cancer with bone metastases, pAKT levels were elevated, and the HER2/CXCR4/AKT pathway was suggested to play an important role in bone metastasis." (PMID 34064589, 2021). "In breast cancer cells, neutralizing NRP2 antibody blocked cytoplasmic C-X-C Motif Chemokine Receptor 4 (CXCR4) expression which was followed by decreased tumor cell migration." (PMID 34239847, 2021). "In breast cancer cells, RGZ inhibits cell invasiveness by blocking the CXCR4 downstream signaling involving FAK, Akt, and ERK." (PMID 34834449, 2021). "We also established a direct connection between the activation of CXCR4 and CCR7, and the inhibition of detachment-induced apoptosis (anoikis) in metastatic breast cancer cells that potentially contributes to the metastatic spread of mammary tumours." (PMID 34685420, 2021). "Our previous results have demonstrated a link between both CXCR4 and CCR7 functional activation and the metastatic potential of breast cancer cells." (PMID 34685420, 2021). "Particularly, in breast cancer, cells IGF1R and CXCR4 directly interact at the cell membrane, and this interaction allows IGF1 to promote cell migration through transactivation of CXCR4." (PMID 33673232, 2021). "Interaction between CXCR4 and its ligand CXCL12 was described to mediate the MDSC trafficking in mouse models of breast cancer and hepatic carcinoma." (PMID 33578808, 2021). "Along similar lines, our results showed that miR-139-mediated CXCR4 reduction correlated with decreased levels of VEGF and IL-6 in the xenograft-transplantation model of human breast cancer." (PMID 34070538, 2021). "Taken together, these results suggest that ATP inhibits bone-tropic breast cancer cells by down-regulating the P2Y11 purinergic receptor and the down-regulation of CXCR4 expression." (PMID 34503103, 2021). "We aimed to investigate the role of miRNA, via CXCR4-modulation, on CSC properties in breast cancer using cell lines and xenotransplantation mouse model and evaluated miR-193 levels in 191 patients with invasive ductal carcinoma." (PMID 34070538, 2021). "Taken together, these results reveal that CXCR4, transcriptionally regulated by ETV4, is a mediator in ETV4-induced SHH pathway activation and stem-like traits in breast cancer cells." (PMID 34052833, 2021). "LNC942 directly recruited METTL14 protein through specific recognition sites, thus enhancing the expression of downstream target genes CXCR4 and CYP1B1 and promoting breast cancer cell proliferation." (PMID 34336856, 2021). "Therefore, drugs targeting CXCR4 may bring good results for breast cancer treatment." (PMID 32253815, 2020). "In breast cancer, the SDF-1/CXCR4 and CXCL5/CXCR2 axes recruit Gr-1+CD11b+ myeloid cells, activate MMP, and upregulate TGF-β1, which contributes to metastasis in mouse models injected with a breast cancer cell line (4T1)." (PMID 32726950, 2020). "Angiopoietin-like protein 2, secreted by breast cancer cells, increases CXCR4 expression in breast cancer, which increases cross-talk between CXCR4 and CXCL12 and, as a result, recruits breast cancer cells to the bone metastatic site." (PMID 32674405, 2020). "Several studies have reported that exosome biomarkers (such as CD44, CD47, CXCR4, Del-1, HER2, and KDR) can be used for early diagnosis and prognosis of breast cancer patients." (PMID 32826923, 2020). "Several transcription factors have been reported to regulate the expression of CXCR4 and CXCL12 in breast cancer cells and those transcription factors can cooperate." (PMID 33096815, 2020). "The CXCR4-targeted dendrimers encapsulating doxorubicin also reduce CXCL12-induced migration of BT-549 and T47D breast cancer cells." (PMID 33096815, 2020).
breast carcinoma (continued). "Additionally, it has been demonstrated that CXCR4 inhibitors (AMD3100 and YN14003) can significantly mitigate tumor progression in HER2 overexpressing breast tumor models thereby indicating that CXCR4 attenuation could be a useful strategy for targeting HER2 breast cancer patients." (PMID 32630806, 2020). "The biological axis of CXCR4 and its receptor CXCL12 (Stromal cell‐derived factor‐1) promotes cancer cell growth, invasion and metastasis in most tumors including breast cancer." (PMID 32253815, 2020). "For example, heparin and Tinzaparin reduced the pulmonary metastasis of breast cancer cells that were over expressing CXCR4 by interfering with the interaction of CXCL12 and its receptor CXCR4." (PMID 32538273, 2020). "Leptin induced the metastasis of breast cancer cells by activating the SDF-1/CXCR4 axis, and upregulation of CXCR4 contributed to bone metastasis and poor survival in breast cancer patients." (PMID 32836215, 2020). "Another study found that CXCL12/CXCR4 signal axis activated HER2 through SRC, promoting the growth and proliferation of breast cancer cells, so that MCF‐7 cells have resistance to tamoxifen." (PMID 32253815, 2020). "A plethora of studies show that CXCR4, the chemokine receptor most commonly overexpressed in cancer, together with its natural chemokine ligand CXCL12 acts as a master regulator of breast cancer tumorigenesis." (PMID 33096815, 2020). "In particular, it has been demonstrated that rosiglitazone reduces the binding of the SDF 1-α secreted by CAFs to the CXCR4 expressed in MCF-7 and MDA-MB-231 breast cancer cells, thus reducing breast cancer cell motility." (PMID 33352766, 2020). "Not only does the future metastatic organ express high levels of CXCL1, but its chemokine receptors CXCR4 and CCR7 are also highly expressed in human breast cancer cells." (PMID 32079335, 2020). "In breast cancer, the CXCL12/CXCR4 axis plays a crucial role in directing the metastasis of CXCR4-positive cancer cells to organs that express high CXCL12 levels, such as the lungs, bone marrow, and lymph nodes." (PMID 32498358, 2020). "In breast cancer brain metastases, the CXCL12/CXCR4 axis takes part in the homing, motility, and progression of metastases to regulate the migration of CTCs through the BBB." (PMID 32751846, 2020). "When combined with eribulin, a chemotherapeutic microtubule inhibitor, a novel CXCL12/CXCR4 antagonist POL5551 reduces metastasis and prolongs survival in mice after resection of the primary breast cancer, compared with single-agent eribulin." (PMID 33123472, 2020). "Examples of this include, the bioactive lipid, lysophosphatidic acid, and its receptor, LPAR-1 in breast cancer, chemokines, CXCL8/IL8 and CXCR1 and CXCR2 in melanoma, pancreatic cancer and gastric tumors and CXCL12 and CXCR4 in multiple cancers." (PMID 33329395, 2020). "Breast cancer cells expressing ACKR3 internalize and degrade CXCL12 leading to its removal from the environment and to decreased CXCR4 signaling." (PMID 33096815, 2020). "In breast carcinoma, brain tumor: glioblastoma, glioma, kidney-related carcinomas, HNSCC, cholangiocarcinoma, stomach, esophageal, and uterine carcinomas, CXCR4 shows significantly higher mRNA expression levels in cancer cells compared to normal counterparts." (PMID 32260318, 2020). "Overall, several strategies to block CXCL12/CXCR4 signaling in breast cancer have been proposed including PPAR-γ agonists, dimerization with other receptors or chemokines and specific CXCR4 inhibitors including AMD3100." (PMID 33096815, 2020). "In patient-derived xenografts, CXCR4 inhibitors AMD3100 and TN14003 block tumor growth and metastasis in both herceptin-sensitive and herceptin-resistant HER2+ breast cancer." (PMID 33096815, 2020).
breast carcinoma (continued). "CXCL12 and RANKL, cytokines that are overexpressed by osteoblast-lineage cells and circulate in the blood, can attract CXCR4 and RANK, which are highly expressed on mammary tumor cells, inducing the latter to migrate to the bone surface." (PMID 32117996, 2020). "Liang reported that the SDF-1/CXCR4 axis can promote the phosphorylation of AKT and then increase the expression of VEGF and promote angiogenesis in breast cancer." (PMID 31382985, 2019). "Previous reports have shown that hypoxia-induced breast cancer cell motility is Rac1 dependent and the Rac1 activity is driven by HIF-1α-mediated transcriptional induction of CXCR4." (PMID 31462898, 2019). "In the breast cancer cell lines MCF7 and SKBR3, the intensity of CXCR4 was statistically increased (p = 0.017 and p = 0.0001 respectively) compared to normal PBMCs." (PMID 31370904, 2019). "Expression of VIM, CDH1, CDH2, PLS3, CXCR4, CD44 and NANOG have been found in healthy controls and the maximal expression levels of these genes were the threshold beyond which CTCs-EBF of breast cancer patients were considered positive." (PMID 30634453, 2019). "In this study, we compared different subtypes of breast cancer cells, and we were interested in the comparative expression of MDM2, MDMX, and CXCR4 in the different contexts." (PMID 30642351, 2019). "For breast cancer, studies have provided evidence for the direct involvement of FAK and members of the Rho family in the CXCR4/SDF-1α-induced migration of tumor cells." (PMID 31219799, 2019). "Muller's study suggested that CXCR4/SDF-1α particularly have prominent roles in primary and metastatic breast cancer, as well as a number of other important malignancies, including lung, brain, and prostate cancers." (PMID 31219799, 2019). "Cytokines such as SDF-1 (CXCL12) produced by CAFs can also promote the proliferation of cancer cells carrying the SDF-1 receptor CXCR4; where SDF-1 expression-level correlates with breast cancer survival." (PMID 30927930, 2019). "Binding of the chemokine CXCL12 to its receptor CXCR4 stimulates downstream G protein signaling, leading to the activation of the PI3K/Akt or MAPK pathway, and the CXCL12/CXCR4 axis is a key step in breast cancer cell migration toward the lungs." (PMID 30893772, 2019). "The higher expression of CXCR4 on tumor cells and intensive generation of SDF-1α from target organs form a major pathway for breast cancer metastasis." (PMID 31219799, 2019). "The CXCL12/CXCR4 axis is strongly correlated with breast cancer aggressiveness and metastasis, whereas the CCL25/CCR9 axis provides chemotherapy resistance to breast cancer cells." (PMID 31616626, 2019). "Similar to CXCR4, CXCR7 binding to SDF-1 is also involved in regulating breast cancer growth and metastasis." (PMID 32047724, 2019). "In summary, our results showed a different CXCR4 and CXCL12 pattern of expression in PT and metastases of cats with mammary carcinoma." (PMID 30012106, 2018). "Although our findings will require a deeper insight into the regulatory pathways involved in the CXCR4/CXCL12 axis, the present study highlights the axis as an important target for future therapy in FMC as it has been proved to be in human breast cancer." (PMID 30012106, 2018). "Similar to CXCR4, ACKR3 is also over expressed in a variety of solid malignancies including prostate and breast cancers and in each of these malignancies it has been shown to drive betta-arrestin-dependent tumor cell adhesion, invasion, survival and growth." (PMID 30257500, 2018). "Remarkably, this compound has the capability to prevent VEGF-mediated tumor angiogenesis induced by the CXCR4/CXCL12 axis in breast tumor xenografts and exerts anti-metastatic activity in breast cancer in cultured cells and animal models." (PMID 30513833, 2018).
breast carcinoma (continued). "Assessment of the expression of other BCSC markers -ALDH1A1, EpCAM, CXCR4, and CD133 in stable NRF1 overexpressing CD44+CD24− and CD44+CD24+ subpopulations showed as many as 10 different downstream breast cancer progenitor cell subpopulations." (PMID 30486409, 2018). "Luminal A (LA), luminal B (LB), normal and basal triple-negative (TN) tumors mimicked the trend of CXCR4 and CXCL12 expression previous described in PT, RM and DM of the total cohort of cats with mammary carcinoma." (PMID 30012106, 2018). "On a preclinical level, TN14003 and AMD3100 (Plerixafor), two anti-CXCR4 inhibitors, have been tested in patient-derived xenografts (PDX) of breast cancer showing antitumor activity in the HER2 subtype." (PMID 30319622, 2018). "In this study, we have demonstrated that in vivo imaging of CXCR4 using the PET probe 68Ga-Pentixafor is feasible in patients with primary and recurrent breast cancer." (PMID 30191351, 2018). "We first studied the effect of TQ on the expression of CXCR4 in MCF7 and MDA-MB-231 breast cancer cell lines." (PMID 30564115, 2018). "Accordingly, MSC facilitated the entry of breast cancer cells into the bone marrow through Tac-1 regulation of SDF-a1 and C-X-C chemokine receptor type 4 (CXCR4)." (PMID 30526687, 2018). "Our results indicate that TQ can down-regulate CXCR4 expression and CXCL12-induced migration and invasion in breast cancer cell lines through inhibition of NF-κB activation." (PMID 30564115, 2018). "The overexpression of MIF in breast cancer cells, and its reported interaction with HSP90 and CXCR-4, is known to induce resistance to apoptosis and stimulation of proliferation via the AKT pathway." (PMID 30060564, 2018). "In summary, we have demonstrated that CXCR4 antagonists protect Jurkat cells against HIV-1 Nef and induce apoptosis in MDA-MB-231 breast cancer cells." (PMID 29682200, 2018). "This work exposes part of the complex interaction between CXCR4 and CXCL12 in PT, but also in metastases of a breast cancer model." (PMID 30012106, 2018). "The current study presents the first results on CXCR4-targeted PET imaging in a larger cohort of patients with primary and recurrent breast cancer." (PMID 30191351, 2018). "One is the chemokine receptor 4 (CXCR4) which we previously demonstrated to be upregulated in BM of NSCLC and breast cancer patients." (PMID 29721166, 2018). "Taken together, our findings presented that NT21MP can regulate expression level of SPRY4-IT1 by blocking SDF-1α/CXCR4 axis and subsequently, activating SKA2 and playing a key role in breast cancer cell apoptosis." (PMID 30104400, 2018). "These various patterns of selectivity seen in the jurkat-NefM1 and breast cancer MB-231 assays can be traced to differing profiles of intrinsic HIV-blocking potency in the MAGI assay and CXCR4 functional response but with some exceptions." (PMID 29682200, 2018). "CXCR4-directed PET imaging in patients with primary and recurrent breast cancer is feasible; however, tumor detectability is significantly lower compared to 18F-FDG PET." (PMID 30191351, 2018). "Receptor expression of the transfected cells in comparison to breast cancer cell lines was evaluated using flow cytometric analyses, showing that MDA-MB-231, MCF-7, SKBR3 and T47D express very low levels of CXCR4." (PMID 30441765, 2018). "Among the small CXCR4 antagonists, the cyclam AMD3465 inhibits breast cancer growth and metastases by acting on both tumor and immune cells." (PMID 30513833, 2018). "Employing orthotopic mammary carcinoma models in a standard readout for the assessment of CSC content, we uncovered an important role of the CXCL12/CXCR4 axis during the early engraftment phase." (PMID 29632733, 2018). "The combined NRF1 overexpression and treatment with E2 also led to reprogramming of CD24+ and CD24−CD44− subpopulations with multiple breast cancer stem cell signatures containing ALDH1A1, EpCAM, CXCR4, or CD133." (PMID 30486409, 2018).
breast carcinoma (continued). "So far, few attempts were made to correlate the expression levels of the SDF-1 receptor, CXCR4 and the different molecular subtypes in human breast cancer." (PMID 29285291, 2017). "The levels of mRNA expression of NF-κB target genes uPA, PAI-1, CXCR4 and MMP-9, all of which strongly correlate with breast cancer metastasis, were measured using quantitative real time PCR." (PMID 28402272, 2017). "We recently reported that E2 controls the activity of the CXCL12/CXCR4/CXCR7 signaling axis in breast tumor cells and influences the proliferation and migration of breast cancer cells." (PMID 28666461, 2017). "It has been reported that BCSCs show a higher rate of bone metastases, compared with parental breast cancer cell line, expressed higher levels of CD44, CXCR4, and osteopontin markers." (PMID 29099748, 2017). "The chitosan nanoparticle delivered siRNA efficiently into breast cancer MCF-7 cells and significantly reduced the expression of CXCR4 in both mRNA and protein levels." (PMID 28446538, 2017). "The overexpression of MIF has been demonstrated in breast cancer cells, in which, through the interaction with HSP90 and CXCR-4, MIF induces resistance to the apoptosis and stimulates the proliferation via AKT pathway." (PMID 28686225, 2017). "The immunohistochemical analysis revealed that CXCR4 is overexpressed in the majority of FMC (36/42; 86%), as previously reported in cat and in breast cancer patients." (PMID 29285291, 2017). "Patients with BAG3 high/CXCR4 high showed worse overall survival than those with BAG3 high/CXCR4 low, confirming the involvement of CXCR4 in oncogenic function of BAG3 in breast cancer." (PMID 28703799, 2017). "Niche interactions mediated by E-cadherin and N-cadherin promote bone colonization by breast cancer cells, and signaling mediated by the chemokine CXCL12 and its receptor CXCR4 facilitates the recruitment of CXCR4+ cancer cells to bone." (PMID 28210624, 2017). "Such a positive correlation between the migration/invasiveness of a cell line and the CXCR4 cell membrane expression has been observed both in EWS and breast cancer cell lines." (PMID 28549419, 2017). "In breast cancer cell lines, CD24 expression reduces stromal cell-derived factor-1-mediated migration and signalling via CXCR4, suppressing their metastatic potential, whilst CD24−/low cells have conversely been shown to increase metastatic potential." (PMID 27189371, 2016). "In human breast cancer, activation of CXCL12/CXCR4 pathway induces the chemotaxis, invasion and metastasis of tumor cells." (PMID 27007162, 2016). "The highly invasive breast cancer lines MDA-MB-231 and DU4475 had CXCR4:GRK3 mRNA expression ratios of 7:1 and 6:1, respectively." (PMID 27049755, 2016). "The G protein coupled receptors (GPCR), such as CXCR4, and its chemokine ligand CXCL12, have been identified as important regulators of metastasis and tumor behavior in breast cancer." (PMID 27049755, 2016). "Taken together, using meta-analysis that combines gene set and network analysis, we suggested CXCR4, CXCL1 and HMGCS1 as candidates involved in tumor stem-like breast cancer cells." (PMID 26870956, 2016). "There have been several reports describing the effects of CXCR4 antagonists (AMD3100, AMD11070 and KRH3955) in the treatment of malignant tumors, including breast cancer, small cell lung cancer, cholangiocarcinoma, gastric cancer and pancreatic cancer." (PMID 27175473, 2016). "Breast cancer cell adhesion and migration through a normal human umbilical vein endothelial cell (HUVEC) monolayer is significantly reduced by inhibiting CXCR4 or treating ECs with an SDF-1 neutralizing antibody." (PMID 27706047, 2016). "Taken together, these results point to a potentially important feed-forward signaling wheel consisting of KLF8, CXCR4 and FAK and CXCL12 is a critical driving force for the cycling of the wheel in breast cancer cells." (PMID 26993780, 2016).